IL13 (interleukin 13)
Diseases named in the same sentence as IL13 in open-access papers (continued):
Sharing a sentence is not in itself a finding about the gene and the disease.
liver fibrosis (continued). "In addition, IL-13 acts as a profibrogenic factor involved in a protective mechanism characterized by formation of CD4+ T cell-driven liver granulomas, which leads to liver fibrosis." (PMID 26258681, 2015). "Although several studies have focused on the contribution of Th2 cells to chronic inflammatory disease and fibrosis, which is characterized by the cytokines IL-4 and IL-13, CD4+ IL-17-secreting T cells have been shown to contribute to pathology in some models of liver fibrosis." (PMID 25590646, 2015). "Besides, gene expressions of Th1/Th2 cytokines such as IL-4, IL-10, IL-13 and IFN-γ, which were important in schistosomiasis liver fibrosis, were also detected in our experiment." (PMID 21629648, 2011). "Conversely, whole blood of fibrosis patients stimulated ex vivo with Schistosoma soluble egg antigen revealed decreased IL‐6, IL‐10, and TNF and elevated IL‐13 in severe hepatic fibrosis compared with nonfibrotic individuals, with IL‐13 again significantly higher in males than females." (PMID 41546136, 2026). "However, the data on clinical applications of this molecular pathway is scarce, as there are no significant studies focusing on IL-13 influence in liver fibrosis." (PMID 41898594, 2026). "Therefore, IL13, IL-33, and TGF-β seem to cooperate, to an extent, for promoting hepatic fibrosis in MASLD and may play a more adverse role in advanced stages of the disease." (PMID 40794228, 2025). "Therefore, we speculated that Sja-miR-71a suppresses liver fibrosis through the Sema4D/TGF-β1 and Sema4D/IL-13 axes." (PMID 32944173, 2020). "Several reports have established the ILC2-derived IL-13 acting on target cells via type II IL-4 receptor as a mechanism for several physiological functions such as beige fat biogenesis or hepatic fibrosis but if ILC2-derived IL-13 can act on autocrine manner has not been established." (PMID 29930549, 2018). "In particular, IL-13 could initiate activation and differentiation of HSCs by enhancing TGF-β signaling through IL-4Rα and signal transducer and activator of transcription 6 (STAT6) in HSCs, promoting liver fibrosis." (PMID 30405626, 2018). "Previous studies have shown that liver fibrosis is involved in the regulation of the deposition of ECM by a complex network of signaling pathways, and we have investigated CGA could regulate liver firbosis through IL-13/miR-21/Smad7 signaling way." (PMID 29311932, 2017). "Given the central function of granuloma in hepatic fibrosis, these findings implied that IL-13 around the Sj egg granuloma was induced by the host inflammatory response to the stimulation of Sj SEA and, thus, accelerated granuloma formation and hepatic fibrosis in Sj infection." (PMID 25110399, 2014). "However, the relationship between IL-13, tTG, and liver fibrosis during Schistosoma infection has not been established." (PMID 25110399, 2014). "Some compensatory mechanisms can possibly increase the level of IL-13 in the blood but not in the liver or some other factors aside from tTG may regulate IL-13 expression correlating with liver fibrosis after Sj infection." (PMID 25110399, 2014). "In liver fibrosis, there is evidence for NK cell regulation of fibrosis in early disease through mediation of cytotoxicity against activated collagen-producing stellate cells via IFN-γ, but also enhancement of late-stage disease through secretion of pro-fibrotic factors, including IL-13." (PMID 23300643, 2012). "The results showed that the changing trend of interleukin-13 (IL-13), transforming growth factor beta (TGF-β), inflammatory factors, and M1, M2 macrophages, were consistent with the development trend of fibrosis regardless of whether liver fibrosis was caused by S. japonicum or CCl4." (PMID 33117360, 2020). "Some other data suggest that IL-13, rather than TGF-β, primarily activates HSCs in liver fibrosis." (PMID 30405626, 2018).
liver fibrosis (continued). "In our research, IL-33 was not significantly upregulated, whereas IL-13, TGF-β1, and type I collagen were highly expressed after infection, indicating that there are alternative pathways that induce overexpression of IL-13 and TGF-β1 and mediate liver fibrosis in BA." (PMID 34858903, 2021).
colitis (125 papers, 2011 to 2026). Inflammation of the colon. "Here, our data suggest that the deficiency of Mcpt-4 triggered a stronger Th2 response in colitis as manifested by increased levels of IL-4, IL-5, IL-10, and IL-13, whereas IL-10 is also generally known as an anti-inflammatory cytokine." (PMID 40697820, 2025). "IL-13 response appears to be a key pathogenic component of the experimental colitis, as IL-13 neutralization prevents its development." (PMID 38137450, 2023). "Perinatal exposure to TiO2 also exacerbated the colitis, as evidenced by a reduced colon length associated with increased colonic mRNA expression and protein levels of IL-1β, IL-4, IL-12, IL-13, IFNγ and TNF-α." (PMID 37996842, 2023). "Many studies suggest that TL1A promotes the development of inflammation by inducing Th2/IL-13 mucosal responses, which are currently considered a main cause of colitis." (PMID 34257516, 2021). "IL-4 and IL-13 have also been reported to play critical pathogenic roles in animal models of colitis." (PMID 33192516, 2020). "Again, they found that only GATA3 overexpression led to more severe colitis with enhanced levels of IL-13, which was causatively involved in the development of colitis." (PMID 33371444, 2020). "Mice of the DSS + PBS group lost weight over time, and weight loss in mice with colitis that were treated with M2 macrophages (DSS + IL-13-cell; DSS + IL-10-cell; and DSS + IL-1β-cell groups) was alleviated." (PMID 31749791, 2019). "A significant up-regulation of genes encoding the following cytokines and their receptors—Il13, Il16, Il27, Il2rb, Il2rg, Il6r Il10ra, Faslg, Ltb, Osm, Spp1, Tnf, Tnfsf14—was noted in animals with colitis (CβG−)." (PMID 31590413, 2019). "Additional studies have expanded on the current understanding of the role IL-13 plays in colitis and describe additional mechanisms associated with IL-13 during colitis." (PMID 30460209, 2018). "In the present study, however, mice with a genetic IL-13 deficiency had significantly more severe colitis after exposure to DSS contrary to that observed in IL-25−/− mice, indicating an anti-inflammatory effect of IL-13." (PMID 25937893, 2014). "Restoration of IL-13 levels in IL-13−/− mice were associated with increased severity of DSS-induced colitis and increased levels of MPO activity." (PMID 24015275, 2013). "Type-2 gut inflammation is not driven by IL-12 and IFN-γ, but is thought to be caused by elevated levels of IL-4, IL-5, and IL-13 and studies have shown a delay in the onset of colitis when IL-4 is blocked by a neutralizing anti-IL-4 antibody." (PMID 22539101, 2012). "The colitis was exacerbated in these animals, as evidenced by a reduced colon length associated with increased colonic mRNA expression and protein levels of IL-1β, IL-4, IL-12, IL-13, IFNγ and TNF-α." (PMID 37996842, 2023). "(50, 100, 200 mg/kg) could protect against the TNBS-caused colitis in a rat model by decreasing the levels of IL-33, IL-5, IL-13, IL-6 cytokines and expression of IL-33 and ST2 proteins to inhibit the IL-33/ST2 signaling pathway." (PMID 36160392, 2022). "Genetically deficient of IL13 in C57BL/6J mice are more susceptible to acute DSS-induced colitis." (PMID 35359953, 2022). "Our previous results have shown that prevention of colitis by immunization with P28GST in the presence of adjuvant was associated with Th2-type regulatory processes such as eosinophil recruitment in lamina propria or increased IL-13 and IL-5." (PMID 30592734, 2018). "To address whether resistance to DSS-induced colitis conferred by IL-25 deficiency was attributable to a defect in IL-13 expression, we exposed IL-13−/− mice to DSS for seven days." (PMID 25937893, 2014). "In contrast to IL-25−/− mice, IL-13−/− mice were more susceptible to DSS-induced colitis." (PMID 25937893, 2014). "This could also be observed in our cellular model of H2O2-associated colitis for Il-13 and TGFβ, whereas levels of Il-6 and Il-8 remained unchanged." (PMID 23742011, 2013).
colitis (continued). "IL-4 and IL-5 expressions were previously quantified in intestinal tissue and correlated with the clinical and histological severity of colitis in UC patients, and IL-13, which was also found to be up-regulated in UC, was linked to an impaired epithelial barrier function in the gut." (PMID 22539101, 2012). "The study revealed that IL-13 induces tissue fibrosis in colitis through a TGF-β1-dependent pathway." (PMID 40093318, 2025). "In colitis mice, treatment with 50 μg TA showed marked increases in IL-13 levels compared to those of untreated colitis mice, reflecting increased eosinophil recruitment to inflamed tissues." (PMID 40333150, 2025). "In colitis mice, however, only IL-13 showed a pronounced increase following 50 μg TA treatment compared to untreated colitis mice, suggesting a selective enhancement of this cytokine in the inflammatory setting." (PMID 40333150, 2025). "IL-13 (p = 0.05) and IL-5Rα (p < 0.05) were significantly increased in the TA-administered colitis group compared with the unadministered colitis group." (PMID 40333150, 2025). "It induces colitis against the Th2-mediated immune response and is characterized by hypersecretion of IL-13 through the activation of intestinal NKT." (PMID 38732497, 2024). "An examination of the expression levels of inflammatory cytokines involved in intestinal inflammation in OXAC confirmed that colitis, which demonstrates a pattern of hypersecretion of IL-5 and IL-13, was induced." (PMID 38732497, 2024). "It induces colitis against the Th2-mediated immune response and is characterized by the hypersecretion of IL-13 through the activation of intestinal NKT." (PMID 38732497, 2024). "Here, HD decreased levels of IFN-γ and IL-13 in mice with colitis, contributing to its anti-inflammatory effect by improving intestinal epithelial barrier function." (PMID 39650157, 2024). "Th2 cells, in contrast, are characterized by their secretion of interleukin-4 (IL-4), interleukin-5 (IL-5), and interleukin-13 (IL-13), which can contribute to the transition from colitis to cancer." (PMID 39575712, 2024). "In this study, after administering Ento-PB to rats with OXZ-induced colitis, the expression levels of IL-13 and TNF-α significantly decreased, while the expression levels of IL-4, IL-10, and EGF sharply increased." (PMID 39230095, 2024). "In experimental mouse models of colitis, IL-4 and IL-13 production contributes to disease pathogenesis with levels increasing progressively from pre- to early- to late-stage disease." (PMID 36749569, 2023). "For example, adoptive transfer of in vitro-derived IL-4/IL-13-stimulated M2a Mφ into mice depleted of resident Mφ resulted in reduced dinitrobenzene sulfonic acid (DNBS)-induced colitis symptoms in mice." (PMID 37768050, 2023). "These alterations were associated with increased susceptibility to colitis and impaired gut barrier function, while administration of IL-13 restored SCFA levels and reduced colitis symptoms in IL-13-deficient mice." (PMID 37836468, 2023). "Previous studies had proven that the IL‐13 level was markedly reduced in DSS‐induced colitis after administrated with probiotics." (PMID 36789079, 2023). "Further studies have shown that Hpb colonization protects mice from TNBS-induced colitis while upregulating the Th2-associated cytokines, IL4, IL5, and IL13, and the regulatory cytokine, IL10." (PMID 37189818, 2023). "Exogenous administration of IL-1β reduces the expression of colonic Th2 cytokines IL-4 and IL-13 and improves colitis, while exogenous IL-18 also reduces the severity of colitis but does not affect the expression of Th2 cytokines." (PMID 37370025, 2023). "In a murine model with oxazolone-induced colitis, which resembles human UC, IL13 is essential for the induction and development of colitis." (PMID 37893107, 2023). "Studies have shown that the type 2 cytokines IL-4 and IL-13 play a major role in macrophage-mediated epithelial wound healing and that they promote colitis alleviation." (PMID 37189566, 2023).
colitis (continued). "As a result, the elevated production of IL13 further contributes to the induction and development of colitis in the IECs-specific Hnrnp I KO mice." (PMID 37893107, 2023). "Histological analysis also showed that blocking IL-13/STAT6 signaling prevented the deterioration of colitis." (PMID 36032134, 2022). "DSS-induced colitis has been shown to induce T-helper cell 2 (Th2) immune responses in the gastrointestinal tract, with IL-4 and IL-13 being identified as important effector cytokines." (PMID 36558966, 2022). "In dextran sulfate sodium (DSS)-induced colitis in a mouse model, IL-13–/– mice administered DSS exhibited significantly reduced colitis severity compared to that of wild-type (WT) mice, accompanied by downregulation of ECs number and colonic 5-HT content." (PMID 35370559, 2022). "As a typical type II cytokine, IL-13 was significantly upregulated and triggered inflammation in oxazolone-induced colitis." (PMID 36032134, 2022). "The qRT-PCR results showed that IL-4, IL-5, and IL-13 levels were significantly higher in the intestinal mucosa of colitis-induced mice than those in the control group (p < 0.05)." (PMID 36359214, 2022). "Oxazolone-induced colitis is primarily driven by robust IL-13 produced from natural killer T (NKT) cells." (PMID 35933374, 2022). "After administration of SI, IL-4, IL-5, and IL-13 levels were significantly reduced in the colonic mucosa of SI-treated mice compared to those in the colitis group (p < 0.05)." (PMID 36359214, 2022). "Nevertheless, the effect of melatonin on type 2 immunity-dependent colitis needs to be documented, as levels of type 2 cytokines, including IL-5 and IL-13, increase in UC patients." (PMID 35116024, 2021). "Recently, an IL-4/IL-13 dual antagonist was developed and evaluated in a murine model of oxazolone-induced colitis, where it showed to ameliorate overall disease activity." (PMID 34737752, 2021). "D5R signaling suppressed the development of experimental colitis by regulating the balance of colonic M1/M2 macrophages, specifically the inhibition of M1 and the promotion of the IL-4/IL-13-triggered M2 macrophage polarization, respectively." (PMID 34884737, 2021). "Indeed, injecting rmIL-33 into mice suffering from acute DSS colitis, strongly abrogated epithelial damage, pro-inflammatory cytokine secretion, and loss of barrier integrity, while it induced a strong increase of Th2 associated cytokines (IL-13/IL-5) in the colon." (PMID 34335571, 2021). "In this stage of colitis, food intake with βGh (CβGh+ group) up-regulated the expression of the Il13, Il21, Il27, and Lta genes and down-regulated the expression of the Il1a, Il11, and Il17a genes." (PMID 33923129, 2021). "Here, we provide evidence that IL-4/IL-13 signalling on intestinal epithelial cells or smooth muscle cells is not important in mediating or preventing exacerbated acute oxazolone-induced colitis." (PMID 32410852, 2020). "In OXZ colitis, IL-4 is the initial cytokine produced by oxazolone colitis, but IL-4 is soon replaced by the production of IL-13, which can activate epithelial cells to secrete mucus and fluid." (PMID 33237174, 2020). "RELMβ expression is induced in mice during DSS colitis, with increased expression requiring IL-13, as IL-13−/− mice were unable to induce RELMβ." (PMID 32508838, 2020). "Our data suggests a redundant role for IL-4/IL-13 signalling on macrophages in acute oxazolone-induced colitis." (PMID 32410852, 2020). "Regarding the role of IL-13 in experimental models of intestinal inflammation, IL-13 blockade ameliorates colitis induced by oxazolone, a murine model resembling some features of UC." (PMID 33371444, 2020). "Based on our results, we concluded that CD4+ T helper- (Th-) type 2 cells producing IL-13 and B cells producing IgE were responsible for mediating colitis in mice." (PMID 32410852, 2020).